MGST2 (microsomal glutathione S-transferase 2)
Description:
Catalyzes several different glutathione-dependent reactions. Catalyzes the glutathione-dependent reduction of lipid hydroperoxides, such as 5-HPETE. Has glutathione transferase activity, toward xenobiotic electrophiles, such as 1-chloro-2, 4-dinitrobenzene (CDNB). Also catalyzes the conjugation of leukotriene A4 with reduced glutathione to form leukotriene C4 (LTC4). Involved in oxidative DNA damage induced by ER stress and anticancer agents by activating LTC4 biosynthetic machinery in nonimmune cells.
Synonyms: GST2; MGST-II
Tractability: Small molecule: a structure with a bound ligand is known. Antibody: its Gene Ontology location is reachable by antibodies, with high confidence; UniProt predicts a signal peptide or a membrane-spanning region. PROTAC: ubiquitination databases record sites on it.
Target class: Enzyme; Transferase
Gene: Protein-coding gene on chromosome 4 (139,665,768 to 139,741,884, forward strand). Ensembl gene ENSG00000085871.
Subcellular location: Endoplasmic reticulum membrane; Microsome membrane
Subcellular location (Human Protein Atlas): Cytosol; Endoplasmic reticulum
Pathways (Reactome):
Metabolism: Aflatoxin activation and detoxification; Glutathione conjugation
Gene Ontology:
Molecular function: glutathione binding; glutathione peroxidase activity; glutathione transferase activity; identical protein binding; leukotriene-C4 synthase activity; protein binding; enzyme activator activity; phospholipid-hydroperoxide glutathione peroxidase activity
Biological process: glutathione biosynthetic process; leukotriene biosynthetic process; lipid catabolic process; lipid metabolic process; positive regulation of inflammatory response; carboxylic acid biosynthetic process; cellular oxidant detoxification; leukotriene metabolic process; response to lipopolysaccharide
Cellular component: endoplasmic reticulum; intracellular membrane-bounded organelle; membrane; plasma membrane; endoplasmic reticulum membrane; nuclear envelope
Genetic constraint (gnomAD): Loss-of-function variants: 5 observed, 11.24 expected, observed/expected ratio (o/e) 0.44, 90% interval 0.23 to 0.94. The upper end of that interval is the gene's LOEUF score, 0.94, which puts it in group 3 of 6, group 1 being the genes least tolerant of losing a copy. Missense variants: 129 observed, 147.71 expected, observed/expected ratio (o/e) 0.87, 90% interval 0.76 to 1.01. Synonymous variants: 71 observed, 63.13 expected, observed/expected ratio (o/e) 1.12, 90% interval 0.93 to 1.37.
Homologues: Orthologues: chimpanzee MGST2 (99% identical), macaque MGST2 (99% identical), dog MGST2 (86% identical), pig MGST2 (85% identical), guinea pig MGST2 (79% identical), rat Mgst2 (79% identical), mouse Mgst2 (75% identical), tropical clawed frog MGST2 (55% identical), zebrafish mgst2 (48% identical). Paralogues in human: LTC4S (44% identical), MGST3 (33% identical), ALOX5AP (33% identical).
Diseases named in the same sentence as MGST2 in open-access papers:
MGST2 is named in the same sentence as 15 diseases in open-access papers, as found by Europe PMC text mining. Sharing a sentence is not in itself a finding about the gene and the disease. The quoted sentences say what the papers report.
Strabismus (3 papers, 2017 to 2024). A misalignment of the eyes so that the visual axes deviate from bifoveal fixation. "In our previous study, we identified the microsomal glutathione S-transferase 2 (MGST2) gene as one of the potential candidates for comitant strabismus susceptibility in a Japanese population." (PMID 38397974, 2024). "MGST2 (microsomal glutathione S-transferase 2 at 4q31.1) was detected as a susceptibility gene for comitant strabismus of esotropia and exotropia by our previous linkage study but was not replicated by the present GWAS." (PMID 39000095, 2024). "In our previous study of linkage analyses, we have reached two potential candidate genes for strabismus susceptibility, MGST2 and WNT2 in chromosomal loci 4q28.3 and 7q31.2, respectively." (PMID 39000095, 2024). "Our results suggest that the MGST2 gene is a potential candidate gene for strabismus susceptibility at the chromosome 4q28.3 locus." (PMID 38397974, 2024). "The aim of this study was to look for the role of the MGST2 gene as a candidate strabismus-susceptibility gene in eye development, eye alignment, and overall eye morphology as possible background for the development of comitant strabismus." (PMID 38397974, 2024). "This study suggests that MGST2 and WNT2 are potential candidates for comitant strabismus in Japanese population." (PMID 29062608, 2017). "This study with different analytical methods for genetic statistics provides evidence that MGST2 and WNT2 are potential candidate genes for comitant strabismus in Japanese population." (PMID 29062608, 2017). "Both MGST2 and WNT2 are known to be expressed in the brain (Jakobsson, Mancini & Ford-Hutchinson, 1996; Cadigan & Nusse, 1997) and likely to be involved in the development of comitant strabismus." (PMID 29062608, 2017).
atherosclerosis (1 paper, 2024). A disease characterized by the build-up of fatty material and calcium deposition in the arterial wall resulting in partial or complete occlusion of the arterial lumen. "MGST2 has been annotated by KEGG as being involved in glutathione metabolism, drug metabolism and resistance, chemical carcinogenesis by receptor activation, as well as fluid shear stress and atherosclerosis." (PMID 39202351, 2024).
breast carcinoma (1 paper, 2022). "RT-qPCR experiments confirmed that our breast cancer cell lines express all three MGSTs (MGST1/MGST2/MGST3) at steady states." (PMID 36293074, 2022).
colon carcinoma (1 paper, 2024). "MGST2 was significantly downregulated after the treatment with a nanozymatic system in CT26 (colon carcinoma) and MKN45 (human gastric adenocarcinoma) cells, as well as in a tumor-bearing mice model." (PMID 39594421, 2024).
gastric tumor (1 paper, 2021). "MGST2 was recently reported as critical in aristolochic acid-induced gastric tumor process." (PMID 34209090, 2021).
type 2 diabetes mellitus (1 paper, 2015). A type of diabetes mellitus that is characterized by insulin resistance or desensitization and increased blood glucose levels. "Eleven genes in the Glutathione metabolism pathway (Gpx7, Gss, Gsta3, Gstm2, Gstm5, Gstm7, Gsto1, Gstp1, Gstt1, Gstt2 and Mgst2) were observed in type 2 diabetes mellitus." (PMID 25788156, 2015).
viral infection (1 paper, 2015). "Among them, 22 genes (Gm26130, mt-Ts2, Mgst2, Cyp7a1, Vps45, etc.)were clustered as a hot block next to a block containing Irf7 gene that is the master regulator for the induction of type I interferon during viral infection." (PMID 25902143, 2015).
tumor (4 papers, 2018 to 2024). "Apart from activated cyclooxygenase in many epithelia-derived malignancies, MGST2 up-regulation may enhance the eicosanoids-mediated crosstalk between tumor cells and the surrounding stromal cells, facilitating a tumor microenvironment." (PMID 32887289, 2020).
cancer (3 papers, 2020 to 2022). A tumor composed of atypical neoplastic, often pleomorphic cells that invade other tissues. "In addition, down-regulation of ALOX5, MGST2, and MGST3 genes using specific siRNAs also decreased platelet-induced cancer cell wound closure and cell migration rate." (PMID 36293074, 2022).
MGST2 also shares sentences with these, for which no sentence is quoted: acute kidney injury (1 paper); Esotropia (1); Exotropia (1); gastric adenocarcinoma (1); hepatocellular carcinoma (1); Salmonella Infections (1).